MC1R (melanocortin 1 receptor)
Diseases named in the same sentence as MC1R in open-access papers (continued):
Sharing a sentence is not in itself a finding about the gene and the disease.
melanoma (continued). "We next examined the potential role of Mc1r in metastasis of melanoma using an established in vivo model." (PMID 22363655, 2012). "We thus generated additional Mc1r-specific siRNA molecules for transfection into B16F10 melanoma cells." (PMID 22363655, 2012). "Recent GWAS have unveiled association between SNPs or genetic variants in MC1R, TPCN2, ASIP, KITLG, SLC24A5, TYR, IRF4, OCA2/HERC2, SLC24A4, SLC45A2, TYRP1, and pigmentation as well as melanoma." (PMID 21559390, 2011). "High expression of the MC1R gene is also typical of the cell lines originating from primary and metastatic melanomas." (PMID 22649681, 2011). "High-frequency alleles with small effects on melanoma risk have also been identified in a number of genes, including MC1R (Melanocortin 1 Receptor) and TYR (tyrosinase)." (PMID 21203498, 2010). "The MC1R gene determines the type of melanin produced in the skin, but its role in melanoma carcinogenesis reaches beyond its pigmentation effects." (PMID 18803811, 2008). "Two high penetrance melanoma susceptibility genes, CDKN2A and CDK4, and a low penetrance gene, MC1R, have been identified." (PMID 18803811, 2008). "Stable transfection of the C8161 melanoma cells with the wild-type MC-1R and the restoration of an α-MSH response provides strong evidence that this peptide is acting by the MC-1R receptor to reduce cell migration." (PMID 15054471, 2004). "Five receptors (MC-1R–MC-5R) have been cloned to date and MC-1R is expressed on human keratinocytes, melanocytes and melanoma cells." (PMID 14612916, 2003). "To further compare the levels of MC1R expression between melanomas and stimulated monocytes, we also performed flow cytometry analysis of melanomas and monocytes stained with fluorescein-conjugated α-MSH." (PMID 12177778, 2002). "We found that MC1R is over-expressed in the majority of the fresh melanoma tissues analysed and also in 20 out of 24 melanoma cell lines but not in carcinoma lines or LCL." (PMID 12177778, 2002). "Collectively, these results demonstrate that MC1R, although strongly expressed in melanomas, is also expressed at lower levels in several normal tissues in situ." (PMID 12177778, 2002). "The immunohistochemical analysis of tissues from human skin and melanoma metastasis in brain allowed us to compare in situ the high expression of MC1R in melanomas with the low expression of this receptor in keratinocytes." (PMID 12177778, 2002). "Melanomas showed two times higher MC1R expression, as compared to LPS-stimulated monocytes, using a fluorescein coupled peptide hormone, and up to five times higher expression using the specific mAb MP1-1B7 in intracellular staining assays." (PMID 12177778, 2002). "The analysed melanocytes expressed detectable levels of MC1R, although the melanoma cell lines tested in parallel showed higher levels of expression." (PMID 12177778, 2002). "We next performed a more extensive analysis of the intracellular expression of MC1R in a series of melanomas and carcinomas." (PMID 12177778, 2002). "In the present study we have analysed several questions relevant to the potential use of MC1R in immunotherapy of melanomas." (PMID 12177778, 2002). "These levels were however lower (30–50%) than those observed in the high MC1R expressing melanoma lines (DFB, FM55, OCM1 and OCM3)." (PMID 12177778, 2002). "Taken together, this confirms that MC1R is expressed at significant levels in activated monocytes, DC cells, and macrophage derived leukaemia cells, although to a lesser extent than in melanoma cell lines." (PMID 12177778, 2002). "Paraffin sections from melanomas or normal tissues were analysed by immunohistochemistry for MC1R expression." (PMID 12177778, 2002). "The potential of targeting melanocortin 1 receptor in therapy and diagnosis will depend on a preferential expression of this receptor in the majority of primary and metastatic melanomas vs normal tissues." (PMID 12177778, 2002).
melanoma (continued). "A more pronounced difference in intracellular expression of MC1R between melanoma lines and cultured monocytes was detected with this method as compared to that found with the α-MSH binding method." (PMID 12177778, 2002). "Next, we compared melanomas and cultured monocytes with regard to their intracellular content of MC1R, as measured by flow cytometry of permeabilised cells using the MP1-1B7 mAb." (PMID 12177778, 2002). "The melanocortin 1 receptor is a G-protein-coupled receptor, described to be expressed on melanomas and melanocytes." (PMID 12177778, 2002). "We have analysed a broad panel of normal tissues by immunohistochemistry and compared their expression of MC1R in relation to melanomas." (PMID 12177778, 2002). "We tested a panel of melanomas, carcinomas and other cell lines for the presence of melanocortin 1 receptor, using two monoclonal antibodies." (PMID 12177778, 2002). "Of these, the melanocortin 1 receptor (MC1R) was originally described to be mainly located on melanoma and melanocytes." (PMID 12177778, 2002). "The possibility of using MC1R for antibody or T cell based immunotherapy is dependent on how selectively this receptor is expressed in melanomas vs normal tissues." (PMID 12177778, 2002). "This demonstrates that in vivo melanoma cells have an increased expression of MC1R compared to normal melanocytes." (PMID 12177778, 2002). "Of particular interest, in vitro activated monocytes and dendritic cells (DC) produced in vitro, also express MC1R although at lower levels than that observed in melanomas." (PMID 12177778, 2002). "Early reports using binding of radiolabelled peptides demonstrated that the MC1R protein is present on the surface of melanoma cells." (PMID 12177778, 2002). "It remains to be seen if the over-expression of melanocortin 1 receptor in melanomas is sufficiently high to allow a ‘therapeutic window’ to be exploited in cancer immunotherapy." (PMID 12177778, 2002). "While MC1R is closely associated with melanoma susceptibility, its impact on ICI efficacy has not been explored previously." (PMID 40926353, 2025). "However, there is also evidence that upregulated MC1R expression in melanomas leads to immune evasion and reduced T cell response by repression of CXCL9-11." (PMID 39935431, 2025). "Moreover, MC1R mutations have a synergistic effect with other melanoma-associated mutations, particularly in CDKN2A and BRAF, further amplifying melanoma risk." (PMID 40507265, 2025). "Although MC1R variants increase susceptibility to melanoma, they do not fully explain individual risk." (PMID 40558591, 2025). "However, in individuals carrying loss-of-function MC1R variants, this protective mechanism is weakened, leading to inefficient repair of UVB-induced mutations and an increased susceptibility to melanoma." (PMID 40507265, 2025). "MC1R was a predictive factor for the prognosis of melanoma patients." (PMID 40213552, 2025). "Additionally, the impact of oxyresveratrol on melanogenesis and the MC1R/cAMP/MITF signaling pathway was evaluated in B16F10 melanoma cells." (PMID 40594379, 2025). "Therefore, in MC1R mutant human melanoma cells, cAMP-dependent activation is disrupted, but the ERK1/ERK2 MAPK pathway functions, leading to a protective role in skin cancer." (PMID 41002740, 2025). "If validated in larger cohorts, MC1R genotyping may serve as a factor helping to predict response to ICIs in melanoma patients." (PMID 40926353, 2025). "However, [[67Cu]Cu-NOTA-PEG2Nle-CycMSHhex] displayed higher cellular uptake that was ~2.5x that of [[67Cu]Cu-NOTA-GGNle-CycMSHhex] in the same MC1R B16/F10 melanoma cell line." (PMID 40430268, 2025). "These radiolabeled probes were developed to target melanoma-specific markers like the melanocortin-1 receptor (MC1R) and melanin itself and have demonstrated specific uptake in melanoma tumors, which helps in tumor visualization while minimizing off-target effects in normal tissues." (PMID 40002300, 2025).
melanoma (continued). "The research indicates that [67Cu]-NOTA-PEG2Nle-CycMSHhexSPECT and [64Cu]-NOTA-PEG2Nle-CycMSHhex PET exhibited favorabletumor targeting and biodistribution characteristics, which highlighttheir potential as MC1R-targeted therapeutic peptides for the treatmentof melanoma." (PMID 39895089, 2025). "Moreover, when the MC1R C315S mouse model was crossed with the melanocyte-specific zDHHC13 transgenic mouse model, UVB-induced melanoma was detected sooner relative to the MC1R R151C mice followed by the wild-type mice." (PMID 40004137, 2025). "Moreover, the MC1R-specific binding of [[64Cu]Cu-NOTA-PEG2Nle-CycMSHhex] was 2.8 times the binding of [[64Cu]Cu-NOTA-AocNle-CycMSHhex] for B16/F10 melanoma cells." (PMID 40430268, 2025). "For example, analyzing pathways linking disease CMM1 to known melanoma-associated genes CDKN2D and CDK4, with edge thickness representing attention weights, revealed a key pathway (CMM1 → MC1R → Mole → CDK4/CDKN2D) offering novel insights into melanoma pathogenesis." (PMID 40680165, 2025). "Combined inhibition of BRAF (by vemurafenib) and HDAC (by 4-phenylbutyrate) upregulated MC1R expression in BRAF-mutant melanoma cells leading to an increased response of BRAFV600E A2058 melanoma-bearing mice to the MC1R-targeting radiolabeled peptide [212Pb]DOTA-MC1L." (PMID 39935431, 2025). "Indeed, ASIP protein is the antagonist of MC1R and GWASs have highlighted an association between ASIP polymorphisms and the risk of melanoma." (PMID 40869905, 2025). "Therefore, this makes MC1R a useful marker for malignant melanoma as well as a potential target for melanoma diagnosis and therapy." (PMID 38256168, 2024). "α-MSH, a ligand specific for MC1R, is overexpressed in both amelanotic and melanotic melanoma, which is significant because it might be used as a vehicle for targeted therapy and imaging." (PMID 39519055, 2024). "Recent scientific evidence suggests that MC1R activation enhances the process of DNA repair, which could potentially prevent melanoma." (PMID 39228912, 2024). "It has been scientifically proven that melanocortin 1 receptors (MC1R) is a powerful regulator of the phosphatase gene (PTEN) following UV exposure, and the mutation of MC1R resulting from excessive UV exposure further enhances the development of melanoma." (PMID 39582871, 2024). "MC1R overexpression can be detected in over 80% of melanoma patients." (PMID 38256168, 2024). "Nonetheless, amelanotic melanoma is often the most difficult to detect because it may exhibit lower MC1R expression." (PMID 39519055, 2024). "Such anti- versus pro-melanoma functions of MC1R may reflect different selection pressures during melanoma initiation versus progression." (PMID 37714844, 2023). "Using tissue microarrays containing three large cohorts of 225 cases of benign nevi, 189 with primary melanoma, and 271 with metastatic melanoma, we applied quantitative immunofluorescence and immunohistochemistry to comprehensively study MC1R protein expression." (PMID 37790306, 2023). "Furthermore, 67Cu-NOTA-PEG2Nle-CycMSHhex exhibited higher MC1R-specific uptake than 67Cu-NOTA-GGNle-CycMSHhex on B16/F10 melanoma." (PMID 37345092, 2023). "The MC1R gene coding for melanocortin 1 receptor, dubbed a ‘youthfulness’ gene, has been found to contribute to facial pigmented spots and skin cancers, including melanoma." (PMID 37924108, 2023). "MC1R gene is polymorphic and frequent variants are associated not only with hair/skin phenotypes but also with increased melanoma risk." (PMID 37608347, 2023). "We therefore tested whether inhibition of cancer cell-derived Cxcl9/10 expression by MC1R signaling is sufficient to mediate immune evasion of B16F10 melanoma." (PMID 37714844, 2023). "However, mutational inactivation of MC1R (Mc1r RHC variants) results in reddened hair color, poorer skin tanning ability in humans, and increases the risk of melanoma." (PMID 36018061, 2023).
melanoma (continued). "The purpose of this study was to perform a mutational analysis of the seven candidate melanoma susceptibility genes (ACD, BAP1, MC1R, MITF, POT1, TERF2IP, and TERT) in high-risk melanoma patients (familial melanoma and MPM) from southeastern Brazil, besides the CDKN2A and CDK4 genes." (PMID 37958811, 2023). "The melanocortin‐1 receptor (MC1R) is a member of the GPCR family that is expressed on melanocytes and enhances ultraviolet (UV) tolerance when activated, which reduces the risk of melanoma." (PMID 36018061, 2023). "As our mRNA data were measured with bulk RNA microarray, one may hypothesise that the MC1R mRNA expression we measured came partly from immune cells instead of melanoma cells." (PMID 37240204, 2023). "It is thus possible to develop antagonists of MC1R to test whether therapeutic blockade of MC1R activation can augment antitumor immunity in melanoma patients." (PMID 37714844, 2023). "Innovative treatment approaches are currently being developed based on MC1R for melanoma." (PMID 37569558, 2023). "In order to examine whether MC1R promotes immune evasion of B16F10 melanoma, we transplanted B16F10-dCas9 cells transduced with NTC or Mc1r sgRNA into mice and monitored tumor growth and host survival over time." (PMID 37714844, 2023). "Most notably, common MC1R variants with an impaired but not absent ability to trigger the cAMP pathway efficiently activated ERKs when expressed in heterologous cells or in melanoma cells." (PMID 37762683, 2023). "Furthermore, specific variants of MC1R are believed to increase the penetrance of CDKN2A mutations, doubling the risk of melanoma compared to a CDKN2A mutation alone." (PMID 37762707, 2023). "There have been some experiments suggesting reduced MC1R expression may contribute to melanoma as melanin cells become less differentiated." (PMID 38256864, 2023). "Pheomelanin-dependent oxidative stress may promote nevus-to-melanoma formation, and detailed analysis in transgenic mouse models may elucidate the role of MC1R/pheomelanin in nevus formation and nevus-to-melanoma transition." (PMID 36834954, 2023). "Taken together, high MC1R expression correlates with low CXCL9/10/11 expression independent of tumor mutation burden in human melanoma." (PMID 37714844, 2023). "Therefore, we sought to determine expression patterns of MC1R in a large cohort of primary or metastatic melanomas and benign nevi using quantitative immunofluorescence to determine expression patterns and intensities." (PMID 37790306, 2023). "The MC1R genotype is a major genetic determinant of melanoma and nonmelanoma skin cancer risk, with frequent variants such as R151C or D294H increasing the odds of developing these diseases." (PMID 37762683, 2023). "No pathogenic variants known for hereditary melanoma were identified, however the female patient showed heterozygosis of two variants in the MC1R gene, conferring a melanoma risk." (PMID 37895483, 2023). "In this review, we explore the molecular biology of α-MSH with particular emphasis into its tumor-related properties, whilst elaborating the experimental evidence currently available regarding the interplay between α-MSH/MC1R axis, melanoma and antitumor strategies." (PMID 37608347, 2023). "MC1R is overexpressed on many mouse and human melanoma cells." (PMID 36144563, 2022). "On the other hand, the top downregulated genes formed 4 subgroups and were related to melanogenesis (Wnt5a, Mitf, Pomc, Mc1r, Kit), melanoma (Fgf9, Fgf12, Fgf2), MAPK signaling pathway (Ncam1, Prkcb, Map3k4, Pla2g4a, Mapk14, Mapk11), and aging (Tgfbr1, Il6, Nox4)." (PMID 36555664, 2022). "MC1-R has myriad ligand affinities and downstream effects and can be found in many cell types, including melanoma, epithelial and endothelial and immune cells Some authors have reported fusion events between macrophages and melanoma cells." (PMID 36499015, 2022).
melanoma (continued). "For example, melanocortin 1 receptor (MC1R) R (D84E, R142H, R151C, I155T, R160W, D294H) variants are associated with the fair skin and red hair color phenotype, which is prone to sunburn and has an increased risk of melanoma." (PMID 36291794, 2022). "The melanocortin-1 receptor (MC1R) has been identified as a G-protein coupled receptor (GPCR) expressed in melanoma cells and melanocytes, which plays an important role in melanoma and skin pigmentation by inhibiting ultraviolet radiation- (UVR-) induced apoptosis, oxidative stress, and DNA damage." (PMID 35140838, 2022). "The hypothesis that locally produced TRH could induce melanoma growth relies on its ability to bind and activate the melanocortin-1 receptor expressed in both melanocytes and melanoma cells." (PMID 36077430, 2022). "αMSH is a cyclic peptide targeting MC1R, which is expressed specifically in melanomas." (PMID 36459299, 2022). "Inherited variation at MC1R is strongly associated with increased risk for melanoma and non-melanoma skin cancers in populations of European ancestry, including among individuals who have limited phenotypic skin cancer risk characteristics." (PMID 35845857, 2022). "In addition, αSyn is shown to reduce UV-induced melanin synthesis in melanoma cells, suggesting a possible inhibitory effect of αSyn on the melanin pathway that is controlled by MC1R." (PMID 35197079, 2022). "Due to the relatively low receptor density of MC1R in melanoma, high molar activity and low injected peptide mass (< 50 pmol per animal) is required for radiopharmaceuticals targeting this receptor to have a good tumour uptake without saturating (blocking) the receptors." (PMID 36459299, 2022). "Inherited anomalies of MC1R play a significant role in melanoma development." (PMID 35334544, 2022). "In addition, the dimerization-defective mutant of the melanocortin-1 receptor (MC1R) both inhibits melanin synthesis and enhances cell migration in human melanoma cells." (PMID 36362939, 2022). "Moreover, we further highlighted the role of targeting BRAF, NRAS and MC1R in melanoma prevention and treatment." (PMID 36551302, 2022). "Thus, MC1R-targeted activation is an effective strategy in melanoma prevention, especially in individuals with red hair and fair skin." (PMID 36551302, 2022). "Results remained consistent before and after removal of the MC1R region (bIVW = 0.06, se = 0.03, pIVW = 0.02), showing that the overall causal relationship between genetic risk of melanoma in females and endometriosis was not driven by the MC1R region." (PMID 36304021, 2021). "Despite the well-established impact of MC1R on skin cancer risk and development, the association of MC1R variants in combination with mutations in susceptible melanoma genes has not been clarified yet." (PMID 34356109, 2021). "We examined public reactions to melanoma genetic testing (using the melanocortin-1 receptor [MC1R] gene) in a study randomizing (like the flip of a coin) 600 diverse primary care patients to a MC1R test offer or usual care." (PMID 34439206, 2021). "Melanomas from non-carriers of MC1R R variants frequently show an atypical pigment network on dermoscopy and are usually SSM, exhibit more dark brown and black colors, asymmetry and structures." (PMID 34440462, 2021). "Interleukin-1-α (IL-1α) and interleukin-1-β (IL-1β) upregulate MC1R mRNA in normal human melanocytes, while TNF-α and TGF-β, that potently repress melanogenesis in melanoma cells, moderately downregulate MC1R expression in normal melanocytes and mouse melanoma cells." (PMID 34356109, 2021). "For example, some allelic variants of the melanocortin 1 receptor (MC1R) can act as genetic modifiers by increasing the penetrance of cyclin-dependent kinase inhibitor 2A (CDKN2A) mutations, doubling the risk of melanoma compared to those only harboring the CDKN2A mutation." (PMID 34442055, 2021).